PPIAP22 (peptidylprolyl isomerase A pseudogene 22)
Synonyms: PPIA3L; formerly PPIAL3
Gene: Processed pseudogene on chromosome 21 (18,857,779 to 18,858,276, forward strand). Ensembl gene ENSG00000198618.
Diseases named in the same sentence as PPIAP22 in open-access papers:
PPIAP22 is named in the same sentence as 3 diseases in open-access papers, as found by Europe PMC text mining. Sharing a sentence is not in itself a finding about the gene and the disease. The quoted sentences say what the papers report.
hepatocellular carcinoma (1 paper, 2021). A malignant tumor that arises from hepatocytes. "In addition, highly expressed pseudogene PPIAP22 promotes hepatocellular carcinoma progression via up-regulating PPIA expression by acting as a ceRNA for miR-197-3p." (PMID 34660601, 2021).
cancer (1 paper, 2021). A tumor composed of atypical neoplastic, often pleomorphic cells that invade other tissues. "To further investigate the underlying function of the PPIAP22/miR-197-3p/PPIA axis in cancers, we found 3,950 genes were significantly positively correlated with PPIA, while 5,909 genes were significantly negatively correlated." (PMID 33790943, 2021). "We found that PPIAP22 was also dysregulated in other types of cancer." (PMID 33790943, 2021). "Thus, PPIAP22 exhibits a widespread impact on cancers and related survival time." (PMID 33790943, 2021). "Among these cancers, only ACC, LIHD, LUAD, and PAAD showed differential relationships between PPIAP22 expression and the DFS or OS of patients." (PMID 33790943, 2021).
tumor (1 paper, 2021). "Among the genes, PPIAP22, a pseudogene, was significantly upregulated in tumor tissues of HCC compared with normal tissues." (PMID 33790943, 2021). "To further investigate the function of the PPIAP22/miR-197-3p/PPIA axis in tumor immunity, we analyzed the expression of PPIA and immune cell infiltration in HCC then by using TIMER." (PMID 33790943, 2021). "Our findings demonstrate that the PPIAP22/miR-197-3p/PPIA axis plays a vital role in the progression of HCC by increasing the malignancy of tumor cells and regulating the immune cell infiltration, especially macrophage, through CCL15-CCR1 or CXCL12-CXCR4/CXCR7 pathways." (PMID 33790943, 2021). "In general, our results suggest a critical role of the PPIAP22/miR-197-3p/PPIA axis in the progression of HCC by increasing malignancy of tumor cells and regulating the immune cell infiltration, especially macrophage, through the CCL15-CCR1 or CXCL12-CXCR4/CXCR7 pathway." (PMID 33790943, 2021). "We also analyzed the correlation between expression of PPIAP22 or PPIA and clinicopathologic features, including gender, age, tumor size, number of tumors, metastasis, and TMN stages." (PMID 33790943, 2021). "PPIAP22 and PPIA mRNA expression levels were also significantly higher in tumor tissues than in normal tissues (p < 0.0001)." (PMID 33790943, 2021). "However, only number of tumors showed significant correlation with expression of PPIAP22 or PPIA when we analyzed the correlation between expression of PPIAP22 or PPIA and clinicopathologic features, including gender, age, tumor size, number of tumors, metastasis, and TMN stages." (PMID 33790943, 2021).